SNORA74 (Small nucleolar RNA SNORA74 )
Gene: Small nucleolar RNA gene on chromosome 17 (15,574,019 to 15,574,198, forward strand). Ensembl gene ENSG00000252129.
Homologues: Orthologues: chimpanzee SNORA74 (98% identical), tropical clawed frog SNORA74 (59% identical), tropical clawed frog SNORA74 (58% identical), tropical clawed frog SNORA74 (57% identical), tropical clawed frog SNORA74 (46% identical). Paralogues in human: SNORA74 (98% identical), SNORA74B (82% identical), SNORA74C-2 (79% identical), SNORA74C-1 (78% identical), SNORA74A (52% identical), SNORA74 (49% identical), SNORA74 (31% identical), SNORA74D (26% identical).